SLC2A9 (solute carrier family 2 member 9)
Diseases named in the same sentence as SLC2A9 in open-access papers (continued):
Sharing a sentence is not in itself a finding about the gene and the disease.
renal hypouricemia (30 papers, 2008 to 2025). "The glucose transporter 9 (GLUT9), encoded by SLC2A9, which causes renal hypouricemia, is reportedly involved in SGLT2 inhibitor-mediated uric acid excretion." (PMID 33922132, 2021). "The loss of function mutations in SLC22A12 and SLC2A9 causes renal hypouricemia (RHUC) type 1 and type 2, respectively." (PMID 32375679, 2020). "SLC2A9 coding for the glucose-facilitated transporter GLUT936, some studies showed renal hypouricemia was caused by dysfunction in the SLC2A9 gene via its decreased urate reabsorption on the renal proximal tubules." (PMID 29453348, 2018). "Mutations in SLC22A12 or SLC2A9 were initially reported in Japanese patients with renal hypouricemia, although patients from various ethnic groups have subsequently been identified." (PMID 30189835, 2018). "Subsequently loss-of-function mutations of SLC2A9 in humans are shown to cause renal hypouricemia, indicating that SLC2A9 plays a critical role in urate reabsorption in the kidney." (PMID 24409316, 2014). "Above all, we conclude that homozygous or compound heterozygous mutations in the SLC2A9 gene are a prerequisite for presenting with EIAKI in patients with renal hypouricemia." (PMID 24628802, 2014). "Stiburkova also reported two renal hypouricemia patients presenting with EIAKI caused by a homozygous G216R mutation or compound heterozygous G216R/N333S mutations in the SLC2A9 gene." (PMID 24628802, 2014). "The GLUT9, encoded by SLC2A9, which causes renal hypouricemia, is reportedly involved in SGLT2 inhibitor-mediated uric acid excretion via an increase in glucose excretion in the urine and an increased exchange of uric acid in the apical membrane of tubular cells." (PMID 34281221, 2021). "Since then, several studies have reported on renal hypouricemia caused by SLC2A9 mutations." (PMID 24628802, 2014). "Significant alterations of SLC2A9 could cause primary renal hypouricemia in people similar to SLC22A12 mutations since genetic heterogeneity exists for this disorder." (PMID 18989453, 2008). "Before the characterization of SLC2A9, most of the clinical studies focused on SLC22A12, and over 90% of renal hypouricemia was reported from SLC22A12 mutations." (PMID 38166558, 2024). "A number of genetic mutations can also cause renal hypouricemia, such as mutations in SLC22A12, which encodes URAT1, and SLC2A9, which encodes GLUT9." (PMID 37108190, 2023). "Hypouricemia caused by a renal tubular defect has been termed “renal hypouricemia”, and loss-of-function mutations of the SLC22A12 and SLC2A9 genes are called type 1 and type 2 renal hypouricemia, respectively." (PMID 36431026, 2022). "Many urate transporter genes, such as SLC22A12/URAT1 and SLC2A9/GLUT9, whose dysfunctional variants cause renal hypouricemia are also reported to have an association with gout and hyperuricemia." (PMID 33517564, 2021). "Renal hypouricemia (RHUC) is a hereditary disorder where mutations in SLC22A12 gene and SLC2A9 gene cause RHUC type 1 (RHUC1) and RHUC type 2 (RHUC2), respectively." (PMID 32375679, 2020). "Renal hypouricemia (RHUC) is caused mainly by urate transporter gene mutations, including SLC22A12 (URAT1) and SLC2A9 (GLUT9/URATv1)." (PMID 30836687, 2019). "The regulation of urate excretion, especially by a cluster of urate transporters in the kidneys, is important in the homeostasis of SUA, which has been corroborated by the presence of type I and type II renal hypouricemia caused by SLC22A12 and SLC2A9 dysfunction, respectively." (PMID 38397902, 2024). "Mutations in the Slc2a9 gene have been shown to be causal for renal hypouricemia, mice lacking the Glut9 protein show early-onset metabolic syndrome." (PMID 34791189, 2022). "Renal hypouricemia is believed to arise owing to genetic defects in SLC22A12 and SLC2A9; this is based on the “rare disease, rare variant hypothesis”38." (PMID 32514006, 2020).
renal hypouricemia (continued). "SLC2A9 (rs7674711) is one of the solute transporter family members involved in blood UA metabolism, and the lack of this protein leads to renal hypouricemia." (PMID 38965453, 2024).
metabolic syndrome (17 papers, 2012 to 2024). A cluster of metabolic risk factors for CARDIOVASCULAR DISEASES and TYPE 2 DIABETES MELLITUS. "SLC2A9 deficiency in mice can induce the occurrence of early-onset metabolic syndrome, suggesting a role of SLC2A9 in regulating enterocyte urate clearance." (PMID 36483739, 2022). "Since SUA is associated with obesity, type 2 diabetes and CVD risk and is advocated by many to be included as a component of the metabolic syndrome, we conducted a measured genotype analysis for SLC2A9 SNPs and these risk factors." (PMID 24379826, 2013). "Moreover, these mice developed early onset metabolic syndromes, including hypertension, dyslipidemia, and hyperinsulinemia, suggesting a role of Slc2a9 in regulating enterocyte urate clearance." (PMID 32850823, 2020). "As metabolic syndrome is a major contributor to the development of T2DM, the rs734553 polymorphism may be the best choice for studying the relation between T2DM and SLC2A9." (PMID 30087870, 2018). "Using urate-associated genetic variants, particularly those within the SLC2A9 locus, as surrogates for the exposure (urate) Mendelian randomization has provided evidence that urate is not causal for ischemic heart disease, metabolic syndrome, reduced renal function, or increased triglyceride levels." (PMID 25889045, 2015). "For example, MUC1, SLC2A9, GCKR, and PKD2 may influence other metabolic syndrome–related traits such as blood pressure and FG." (PMID 31408958, 2019).
Hypertension (14 papers, 2013 to 2024). The presence of chronic increased pressure in the systemic arterial system. "There was an association between the T allele at rs16890979 (SLC2A9 gene) and hypertension with aOR (95%CI) 1.17 (1.06–1.29), pcorr 0.0355." (PMID 35633389, 2022). "Different studies demonstrated that polymorphisms of the SLC2A9 gene associate with the risk of hypertension." (PMID 33498870, 2021). "On the contrary, an Mendelian randomization study employed rs16890979 (SLC2A9) as the instrument and found causal associations between uric acid with hypertension." (PMID 32258131, 2020). "We extend these findings to the analysis of association of SLC2A9 with cardiovascular and renal factors given the role of SLC2A9 in hypertension and renal urate transport." (PMID 24379826, 2013). "It reported a statistically significant negative association between SNPs in the ABCG2 and SLC2A9 genes that are associated with high SU and hypertension with evidence of dose response." (PMID 35633389, 2022). "Rs3775948.GG of SLC2A9/GLUT9, rs504915.AA of NRXN2/URAT1, and 7 clinical features (age, hypertension, nephrolithiasis, blood glucose, serum urate, urea nitrogen, and creatinine) were generated by LASSO." (PMID 35264217, 2022). "The variability in the serum UA concentrations was best explained by sex; age; BMI; hypertension; hyperglycemia; the serum levels of triacylglycerols, creatinine and GGT; allopurinol intake, MTHFR c.1286A>C, ABCG2 c.421C>A, SLC2A9 c.844G>A and SLC2A9 c.881G>A." (PMID 24827988, 2014). "After adjusting for multiple testing, there was a statistically significant positive association between urate lowering allele at SLC2A9 and hypertension, and negative association between urate raising allele at ABCG2 and hypertension (OR 1.17 and OR 0.86, respectively)." (PMID 35633389, 2022). "However, polymorphisms involving major urate transporters genes (e.g., SLC2A9) have not been demonstrated to correlate with hypertension." (PMID 33498870, 2021).
diabetes (13 papers, 2009 to 2025). "Previous studies have shown that the SLC2A9 rs1014290 SNP was associated with the risk of diabetes, and that the GG genotype played a protective role in the occurrence of T2DM; however, another study concluded that this protective role was not related to the level of blood UA." (PMID 36545489, 2022). "SLC2A9 encodes GLUT9, and SNPs in SLC2A9 are not only associated with UA levels, but also with pancreatic β-cell function and diabetes." (PMID 36545489, 2022). "Studies have reported that SLC2A9 is expressed in both kidney and liver of human and mice and is upregulated in diabetes mice." (PMID 26902266, 2016). "The A/G (rs1014290) SNP in SLC2A9 is closely related to the occurrence and development of diabetes." (PMID 36545489, 2022). "Similarly, another SLC2A9 variant (rs1014290), associated with lower SUA were also associated with decreased risk for diabetes mellitus in Han Chinese." (PMID 24379826, 2013). "However, neither SLC2A9 nor SLC5A1 has been shown to be closely associated with diabetes and this is reflected in the descriptive text in OMIM, which is very brief." (PMID 19575795, 2009). "SLC2A9 and SLC5A1 are both glucose transporters over the cell membrane and are as such interesting candidate genes for diabetes." (PMID 19575795, 2009). "DNA methylation of genes identified such as SLC2A9, HOOK2, LTF, and DUSP22 all have direct or indirect links to diabetes or obesity including immune or inflammatory regulatory pathways, signaling pathways, and clinical disorders related to diabetes and obesity." (PMID 32075680, 2020).
renal hypouricemia type 2 (10 papers, 2014 to 2025). "All these findings indicate that the SLC2A9 variant p.(R198H) is pathogenic and causes renal hypouricemia type 2 by decreasing urate reabsorption in the proximal tubule." (PMID 37176161, 2023). "Mutations of SLC2A9 lead to poor reabsorption and Renal Hypouricemia type-2, as caused by increased urate excretion." (PMID 35154085, 2021). "It was discovered that SLC2A9 polymorphisms cause renal hypouricemia type 2 by reducing the urate transport activity leading to lowering renal urate reabsorption and lower serum urate." (PMID 33087043, 2020). "First, human mutations of SLC2A9 lead to Renal Hypouricemia type 2 (RHUC-2, OMIM #612067), a monogenic disease characterized by very low SUA (decreased by 70 to 90%), high fractional excretion of urate and occasional exercise-induced acute renal failure." (PMID 29967582, 2018). "This case report highlights the complexity of Renal Hypouricemia Type 2 (RHUC2) associated with compound heterozygous mutations in the SLC2A9 gene in a 30-year-old Indian male with recurrent exercise-induced acute kidney injury (EIAKI)." (PMID 39421323, 2024). "Loss-of-function mutations in the SLC22A12 gene cause renal hypouricemia type 1 (RHUC1), whereas renal hypouricemia type 2 (RHUC2) is caused by mutations in the SLC2A9 gene." (PMID 24397858, 2014). "The homozygous SLC2A9 c.224T>G, p.Leu75Arg variant, identified in a 71-year-old patient with hypouricemia and AKI, is consistent with renal hypouricemia type 2 (RHUC2)." (PMID 40429823, 2025). "Renal hypouricemia type 2 (RHUC2, MIM#612076) is a disorder caused by defects in the SLC2A9 gene encoding the facilitative glucose transporter 9 (GLUT9)." (PMID 24397858, 2014). "Currently, only two urate transporters related to the Mendelian disorders have been reported: SLC22A12 (OMIM 220150), which is responsible for renal hypouricemia type 1 (RHUC1), and SLC2A9 (OMIM612076) which is responsible for renal hypouricemia type 2 (RHUC2)." (PMID 38166558, 2024).
acute kidney injury (7 papers, 2014 to 2025). Sudden and sustained deterioration of the kidney function characterized by decreased glomerular filtration rate, increased serum creatinine or oliguria. "It is well known that SLC2A9 gene mutation causes hereditary renal hypouricemia type 2 (RHUC2), which is characterized by severe hypouricemia and easy to be complicated with acute renal failure and renal calculi." (PMID 35922835, 2022).
nephrolithiasis (7 papers, 2011 to 2024). The presence of a calculus in the pelvis of the kidney; this is most often composed of mineral salts and proteins. "Furthermore, individuals with SLC2A9 mutations, especially those who are homozygous, appear to be more susceptible to EIAKI and kidney stones." (PMID 38384421, 2024).
Obesity (7 papers, 2012 to 2025). Accumulation of substantial excess body fat. "In addition, SLC2A9 single nucleotide polymorphisms (SNPs) and plasma uric acid were associated with obesity; results that were further replicated." (PMID 41159936, 2025). "Obesity and SLC2A9 genotype are strong determinants of uric acid levels." (PMID 23272134, 2012).
type 2 diabetes (7 papers, 2011 to 2022). "Three of the GWAS genes (SLC2A9, CACNA1D and CSMD1), one in the chromosome 12 and two in the chromosome 16 synteny groups, harboured SNPs significantly associated with both blood pressure and insulin resistance/type 2 diabetes in humans." (PMID 28130354, 2017).
chronic kidney disease (5 papers, 2018 to 2025). Impairment of the renal function secondary to chronic kidney damage persisting for three or more months. "The rs734553 located on the intron 7 of SLC2A9 in human is greatly related with serum uric acid of healthy individuals with normal renal function, thus it is powerful for prediction of chronic kidney disease progression." (PMID 31419940, 2019). "If young people aged 18–40 have normal kidney function and they develop hyperuricemia, the most likely clinical indication is genetic variants in urate transporters, such as SLC2A9, rather than underlying chronic kidney disease." (PMID 34063419, 2021).
coronary heart disease (4 papers, 2014 to 2019). "but it was based on a single urate-associated variant in SLC2A9 (rs7442295), and, although the sample size was fairly large, it included only one-ninth of the number of coronary heart disease cases incorporated in the present analysis." (PMID 26781229, 2016).
Parkinson disease (3 papers, 2011 to 2017). A progressive degenerative disorder of the central nervous system characterized by loss of dopamine producing neurons in the substantia nigra and the presence of Lewy bodies in the substantia nigra and locus coeruleus. "The complexity in the SLC2A9 polymorphism was demonstrated further in two recent studies linking SUA levels with human cognitive aging and Parkinson's disease." (PMID 21886828, 2011). "Individuals with Parkinson's disease (PD) have lower uric acid levels than those without PD, and the CC genotype and C minor allele of a single nucleotide polymorphism (SNP), rs1014290 of SLC2A9, are associated with lower uric acid levels." (PMID 29158942, 2017).
gastric cancer (2 papers, 2015 to 2023). A primary or metastatic malignant neoplasm involving the stomach. "Meantime, lower SLC2A9 mRNA levels were significantly associated with poorer survival in the patients with gastric cancer." (PMID 38021150, 2023). "Notably, samples from four tumor types (prostate, renal, testis, and andrenal) showed reduced SLC2A9 expression, and survival is better in gastric cancers with higher SLC2A9 expression." (PMID 25889045, 2015).
social phobia (2 papers, 2013 to 2020). An anxiety disorder characterized by an intense, irrational fear of one or more social or performance situations in which the individual believes that he or she will be scrutinized by others. "The results of the genetic associations for social phobia using the SLC2A9 rs6855911 variant serve to validate the findings of the observational analysis." (PMID 24204615, 2013). "We observed a similar quadratic relationship between SLC2A9 rs6855911 (associated with increasing levels of uric acid) and social phobia when keeping both men and women in the analysis." (PMID 24204615, 2013). "Further analyses using SLC2A9 rs6855911 variant, known to be strongly associated with SUA, supported the quadratic relationship observed between SUA phenotype and social phobia." (PMID 24204615, 2013). "While not much is known regarding its role in the brain, SLC2A9 SNPs have been associated with better memory performance, and social phobia." (PMID 32174962, 2020).
anxiety disorder (1 paper, 2013). A category of psychiatric disorders which are characterized by anxious feelings or fear often accompanied by physical symptoms associated with anxiety. "The next set of analyses explored the association of uric acid with anxiety disorders using SLC2A9 rs6588911 variant instead of phenotypic values for SUA." (PMID 24204615, 2013). "Additionally, we examined the association of SLC2A9 rs6855911 variant with anxiety disorders." (PMID 24204615, 2013). "In addition, we examined the associations between a key variant of the SLC2A9 gene which has been shown to have a strong association with SUA in genome-wide association studies and anxiety disorders." (PMID 24204615, 2013).
bipolar disorder (1 paper, 2023). A disorder of the brain that causes unusual shifts in mood, energy, activity levels and the ability to carry out day-to-day tasks. "However, since PSI regulatory elements conveying evolution perspectives, they can bring new insights into complex regulation mechanisms as shown in the LRP4 example here and previous examples of SLC2A9 regulating urate levels and CACNA1C regulating Bipolar Disorder and Schizophrenia." (PMID 37056664, 2023).
breast carcinoma (1 paper, 2021). "Additionally, there is a certain interaction between abnormal mRNA expression of SLC2A6, SLC2A8, SLC2A9 and prognosis in breast cancer (HR: 1.13 [1.06–1.62];p = 0.013, HR: 1.28 [1.03–1.59];p = 0.027 and HR: 0.78 [0.61–0.99];p = 0.043, respectively)." (PMID 34488531, 2021).
breast tumors (1 paper, 2023). "Specifically, SLC2A1, SLC2A6, SLC2A10, and SLC2A13 were significantly overexpressed, whereas SLC2A3, SLC2A4, SLC2A9, SLC2A11, and SLC2A12 had downregulated expressions in breast tumors compared with those in normal breast epithelium." (PMID 37108300, 2023).
Cognitive impairment (1 paper, 2021). Abnormal cognition is characterized by deficits in thinking, reasoning, or remembering. "In accordance with our results, it has been reported that DRD1, DRD2, DRD3, DRD4, and SLC2A9 are associated with cognitive performance or cognitive impairment." (PMID 34285142, 2021).
microtia (1 paper, 2014). "Based on the knowledge that microtia is one of the facial deformities with cartilage abnormity, we suggest detailed investigations on the EVC, EVC2, SLC2A9, NKX3-2 and HMX1 genes for this isolated microtia pedigree." (PMID 24983964, 2014).
testicular cancer (1 paper, 2023). A primary or metastatic malignant neoplasm that affects the testis. "A study revealed that SLC2A9 mRNA expression levels were significantly lowered in a variety of cancer tissues, including kidney, prostate, and testicular cancers." (PMID 38021150, 2023).
cancer (6 papers, 2015 to 2025). A tumor composed of atypical neoplastic, often pleomorphic cells that invade other tissues. "Furthermore, decreased SLC2A9 expression was observed in several cancer types and was associated with a poorer prognosis." (PMID 36814289, 2023). "Inhibition of SLC2A9 activity by use of small interfering RNAs or the urate-lowering drugs probenecid and benzbromarone increases ROS levels in a urate-dependent manner and increases susceptibility of cancer cells to apoptotic cell death induced by the chemotherapeutic agent cisplatin." (PMID 25889045, 2015). "There could be therapeutic potential in inhibiting SLC2A9 in order to chemosensitize cancer cells by increasing ROS levels." (PMID 25889045, 2015). "Collectively, these data implicate a role for SLC2A9 in countering intracellular ROS by transport of urate (which reduces ROS) and provide support for the controversial hypothesis (based on observational data) linking uric acid to protection from cancer." (PMID 25889045, 2015).